SNTA1 (syntrophin alpha 1)
Description:
Adapter protein that binds to and probably organizes the subcellular localization of a variety of membrane proteins. May link various receptors to the actin cytoskeleton and the extracellular matrix via the dystrophin glycoprotein complex. Plays an important role in synapse formation and in the organization of UTRN and acetylcholine receptors at the neuromuscular synapse. Binds to phosphatidylinositol 4,5-bisphosphate (By similarity).
Synonyms: TACIP1; SNT1; LQT12; dJ1187J4.5
Tractability: Antibody: its Gene Ontology location is reachable by antibodies, with high confidence; UniProt places it where antibodies can reach, with medium confidence. PROTAC: ubiquitination databases record sites on it; its protein half-life has been measured.
Gene: Protein-coding gene on chromosome 20 (33,407,955 to 33,443,885, reverse strand). Ensembl gene ENSG00000101400.
Subcellular location: Cell membrane, sarcolemma; Cell junction; Cytoplasm, cytoskeleton
Pathways (Reactome):
Extracellular matrix organization: Formation of the dystrophin-glycoprotein complex (DGC)
Gene Ontology:
Molecular function: ATPase binding; nitric-oxide synthase binding; protein binding; sodium channel regulator activity; transmembrane transporter binding; dystroglycan binding; molecular adaptor activity; PDZ domain binding; structural molecule activity
Biological process: regulation of heart rate; regulation of sodium ion transmembrane transport; regulation of ventricular cardiac muscle cell membrane repolarization; ventricular cardiac muscle cell action potential; camera-type eye development; muscle contraction; positive regulation of Rac protein signal transduction; synaptic signaling
Cellular component: protein-containing complex; dystrophin-associated glycoprotein complex; lateral plasma membrane; neuromuscular junction; plasma membrane; sarcolemma; syntrophin complex; anchoring junction; cytoskeleton
Genetic constraint (gnomAD): Loss-of-function variants: 32 observed, 43.83 expected, observed/expected ratio (o/e) 0.73, 90% interval 0.55 to 0.98. The upper end of that interval is the gene's LOEUF score, 0.98, which puts it in group 4 of 6, group 1 being the genes least tolerant of losing a copy. Missense variants: 575 observed, 630.85 expected, observed/expected ratio (o/e) 0.91, 90% interval 0.85 to 0.98. Synonymous variants: 300 observed, 281.91 expected, observed/expected ratio (o/e) 1.06, 90% interval 0.97 to 1.17.
Gene-disease validity (ClinGen):
ClinGen rates the evidence that SNTA1 causes each of these diseases.
long QT syndrome (autosomal dominant): Disputed.
Homologues: Orthologues: chimpanzee SNTA1 (99% identical), dog SNTA1 (93% identical), rat Snta1 (93% identical), guinea pig SNTA1 (92% identical), mouse Snta1 (92% identical), pig SNTA1 (91% identical), rabbit SNTA1 (90% identical), tropical clawed frog snta1 (62% identical), zebrafish SNTA1 (40% identical), Drosophila melanogaster Syn1 (40% identical), Caenorhabditis elegans stn-1 (34% identical). Paralogues in human: SNTB1 (50% identical), SNTB2 (48% identical), SNTG2 (29% identical), SNTG1 (27% identical).
Diseases named in the same sentence as SNTA1 in open-access papers:
SNTA1 is named in the same sentence as 21 diseases in open-access papers, as found by Europe PMC text mining. Sharing a sentence is not in itself a finding about the gene and the disease. The quoted sentences say what the papers report.
long QT syndrome (7 papers, 2019 to 2025). "SNTA1 has also been shown to play a key role in the genetic regulation of ventricular cardiac muscle cell membrane repolarization, with variants linked to atrial fibrillation and long QT syndrome (LQTS)." (PMID 39900885, 2025). "Additionally, the genetic dimension comes into play, with microarray analysis revealing differential expression of KCNH2, SCN5A, and SNTA1—genes associated with long QT syndrome—when cells are treated with ribociclib." (PMID 39254653, 2024). "Mutations in the SNTA1 gene are known to be associated with a long QT syndrome, which is like other long QT syndromes characterized by prolonged QT intervals and arrhythmias, which may result in sudden death." (PMID 32927262, 2020). "AC9 proximal proteins SNTA1 and dystroglycan (DAG1) regulate Nav1.5 currents and are linked to arrhythmia-prone long QT syndrome, Brugada’s syndrome, and muscular dystrophy, respectively." (PMID 40749829, 2025). "NaV1.5 regulatory proteins caveolin 3 (CAV3), alpha 1 syntrophin (SNTA1), and cardiac sodium channel beta subunit 4 (SCN4B) have been reported in association with rare subtypes of congenital long QT syndrome." (PMID 31336969, 2019).
breast carcinoma (2 papers, 2012 to 2022). "SNTA1 signaling axis plays an essential role in cytoskeletal organization and is also implicated in breast cancers." (PMID 35273919, 2022). "In addition, we found that loss of SNTA1-p66Shc interaction impaired actin organization, proliferation, and migration in breast cancer cells." (PMID 35273919, 2022). "Although, SNTA1 signaling pathway has been implicated in dynamic remodeling of actin cytoskeleton, but the precise mechanism/s involved in SNTA1 mediated actin modulation in metastatic breast cancers are still unknown." (PMID 35273919, 2022). "Here, we demonstrate a crucial role for the actin cytoskeletal modulation in driving SNTA1/p66Shc signal transduction mediated pro-metastatic phenotypes in breast cancer cells." (PMID 35273919, 2022). "The present data clearly indicates that actin cytoskeleton is involved in maintenance of SNTA1-p66Shc interaction in metastatic breast cancer cells." (PMID 35273919, 2022). "In summary, we have demonstrated reciprocal regulation between actin modulation and SNTA1/p66Shc/RhoA signaling cascade in human metastatic breast cancer cells." (PMID 35273919, 2022). "Our results demonstrate a novel reciprocal regulatory mechanism between actin modulation and SNTA1/p66Shc/RhoA signaling cascade in human metastatic breast cancer cells." (PMID 35273919, 2022). "Here, in this study, we have analyzed the dynamic interplay between actin modulation and SNTA1/p66Shc mediated signaling in regulating cellular events like proliferation, migration as well as cytoskeletal organization in human breast cancer cells." (PMID 35273919, 2022). "In addition, it has previously been shown that SNTA1/Grb2/p66Shc signaling complex enhances Rac1 activation that in turn augments metastatic characteristics of breast cancer cells." (PMID 35273919, 2022). "As shown in the results above, SNTA1/p66Shc signaling axis contributed to RhoA activation in metastatic breast cancer cells; whereas cytochalasin D mediated actin depolymerization destabilized this transduction axis reducing RhoA activation levels in these cells." (PMID 35273919, 2022).
sudden infant death syndrome (2 papers, 2017 to 2025). Unexpected death in infancy which remains unexplained following autopsy, review of the medical history, and investigation of the death circumstances and death scene. "Mutations in four of these genes, i.e. GPD1L, MOG1, SNTA1, CAV3 have been linked with AF and long QT syndrome (LQTS), Brugada syndrome (BrS) or sudden infant death syndrome (SIDS)." (PMID 28837624, 2017).
amyloidosis (1 paper, 2022). A disorder characterized by the localized or diffuse accumulation of amyloid protein in various anatomic sites. "To evaluate whether loss of perivascular AQP4 localization increases Aβ levels, we evaluated the effect of Snta1 gene deletion within the Tg2576 amyloidosis line, comparing soluble and insoluble Aβ levels by ELISA in Tg2576:Snta1−/− mice and Tg2576:Snta1+/+ littermate controls at 6 months of age." (PMID 35473943, 2022).
Arrhythmia (1 paper, 2025). Any cardiac rhythm other than the normal sinus rhythm. "The few contractile-related proteins labeled by AC9 were associated with cardiac arrhythmias, including SNTA1 and desmoglein (DSG2)." (PMID 40749829, 2025). "Although AC9 labeled few selective cardiac proteins, its proximity to AKAP5 and SNTA1 (and weak labeling of KCNQ1, SS = 0.5) is in accord with its roles in cardiac repolarization and inheritable arrhythmias." (PMID 40749829, 2025).
dementia (1 paper, 2018). Loss of intellectual abilities interfering with an individual's social and occupational functions. "Using human transcriptomic data, we demonstrate that expression of perivascular astroglial gene products dystroglycan (DAG1), dystrobrevin (DTNA) and alpha-syntrophin (SNTA1), are associated with dementia status and phosphorylated tau (P-tau) levels in temporal cortex." (PMID 30120299, 2018).
Duchenne muscular dystrophy (1 paper, 2022). Duchenne muscular dystrophy (DMD) is a neuromuscular disease characterized by rapidly progressive muscle weakness and wasting due to degeneration of skeletal, smooth and cardiac muscle. "SNTA1 expression prevents reentrant arrhythmias in Duchenne Muscular Dystrophy (DMD) iPSC-CM monolayers." (PMID 35762211, 2022).
myocardial diseases (1 paper, 2022). "SNTA1-deficient cardiomyocytes can be used to research the etiology, pathogenesis, and potential therapies for myocardial diseases." (PMID 35773684, 2022).
Ventricular arrhythmia (1 paper, 2015). "ATP2B4 encodes a plasma membrane calcium ATPase that mediates neuronal nitric oxide signaling in cardiac myocytes and directly interacts with a gene, SNTA1, that has been implicated in hereditary ventricular arrhythmia and sudden, presumed arrhythmic infant death." (PMID 26448358, 2015).
SNTA1 also shares sentences with these, for which no sentence is quoted: Brugada syndrome (2 papers); cardiomyopathies (2); muscular dystrophy (2); tumor (2); atrial fibrillation (1); cancer (1); cardiac arrhythmias (1); channelopathies (1); diabetes mellitus (1); long QT syndrome 12 (1); type 1 diabetes (1); Type 2 diabetes (1).